SREBF1 (sterol regulatory element binding transcription factor 1)
Diseases named in the same sentence as SREBF1 in open-access papers (continued):
Sharing a sentence is not in itself a finding about the gene and the disease.
tumor (continued). "The differential expression of ATP citrate lyase (ACLY), acetyl-CoA carboxylase alpha (ACACA), fatty acid synthase (FASN), SCD, and SREBF1 was further validated via RT‒qPCR subsequent to magnetic-based cell sorting of co-cultured H2228 and H3122 tumor spheroids." (PMID 40524253, 2025). "Sterol regulatory element-binding transcription factor 1 (SREBF1) is a pivotal transcription factor governing lipid synthesis, uptake, storage, and release, thereby maintaining lipid homeostasis and supporting rapid tumor growth." (PMID 39962068, 2025). "There exists a research gap regarding the roles of SREBF1 in the tumor immune microenvironment, and our findings indicate that focusing on SREBF1 could be a hopeful strategy for immunotherapy." (PMID 40668814, 2025). "The findings suggest that inhibiting SREBF1 with fatostatin could suppress PCa tumor growth, especially in cases with high BHLHE40 expression." (PMID 38064101, 2024). "Seven potential tumor antigens, [SREBF1, LUC7L3, LAMA5, PCGF3, HNRNPH1, KLC4, and OFD1], which were associated with nonsense-mediated mRNA decay factor expression, overall survival, and infiltration of APCs and would thus induce a potent anti-tumor T-cell response." (PMID 39399167, 2024). "In addition, high expression of SREBF1 correlated with tumor stage, lymph node stage, and tumor grade in HNSC, suggesting that SREBF1 plays an important role in the progression of HNSC." (PMID 37090107, 2023). "Although discrete, these two events converged into a single outcome; dual-phosphorylated SREBF1 ‘sensed’ the lack of androgen, and triggered deposition of epigenetic event, H2A-K130ac in SREBF1 genetic locus to initiate cholesterologenic program in tumor cells." (PMID 37296155, 2023). "Thus, increased expression of SREBF1 can aid in the increased demands of lipids for tumour cell proliferation." (PMID 35710732, 2022). "However, all 6 mice that were injected with SREBF1 expressing cells formed robust tumor growth." (PMID 37296155, 2023). "Nonetheless, despite successfully inhibiting BRD1, we observed a concurrent downregulation of SREBF1, FASN and SCD1 within the HCC tumor tissue." (PMID 39962068, 2025). "Previous studies have proven that SREBF1, GPNMB, and HIF1A can promote primary tumor growth in a variety of cancers." (PMID 40095604, 2025). "SE promotes lipid synthesis pathways by regulating sterol regulatory element binding transcription factor 1 (SREBF1) and SREBF2, meeting the high demand of tumor cells for lipids." (PMID 40032852, 2025). "Further, immunohistochemical (IHC) analysis of tumor tissues confirmed that the combination of α-hederin and PTX significantly decreased the expression of SREBF1, FASN, phosphorylated SMAD2, and the sEVs-marker protein TSG101 compared to PTX alone." (PMID 38362150, 2024). "SREBF1 and FASN, as important checkpoints of lipid metabolism, have been suggested to mediate tumor therapy resistance." (PMID 38362150, 2024). "SREBF1 was significantly upregulated in several tumor tissues, including HNSC, and SREBF1 overexpression was positively correlated with sample type, cancer stage, tumor grade, and lymph node stage in HNSC patients." (PMID 37090107, 2023). "Further analysis of the TCGA database revealed that SREBF1 and STARD4 expression is significantly higher in HNSC tumor tissues than in adjacent normal tissues." (PMID 37090107, 2023). "Analysis of the UALCAN database indicated that the expression of SREBF1 and STARD4 correlated with sample type, tumor stage, lymph node stage, and tumor grade." (PMID 37090107, 2023). "In vivo, this extract produced a significant tumor growth inhibition, a decrease in KI67-positive cells and a downregulation in SREBF1." (PMID 36362920, 2022). "The RT-qPCR results revealed that SREBF1 and FASN showed significantly high expression in ten IMPC and nine IDC-NOS tumor tissues, respectively (Student’s t-test, P = 0.013 and 0.037)." (PMID 34799559, 2021).
tumor (continued). "Furthermore, this dual inhibition strategy attenuates the recruitment of sterol regulatory element binding transcription factor 1 (SREBP1) and p300 to genes essential for cholesterol synthesis, thus hindering tumor growth." (PMID 39656925, 2025). "Notably, the expression levels of SREBF1, FASN and SCD1 were significantly decreased in the tumor tissues of iBRD1 and simvastatin treated animals." (PMID 39962068, 2025). "In addition, our analysis of HNSC data from TCGA revealed that both SREBF1 and SCD were overexpressed in tumor tissues." (PMID 40712780, 2025). "Indeed, it was found that NH4+ plays a key role as an activator of sterol regulatory element-binding transcription factor 1 (SREBP-1), promoting lipogenesis and tumor progression in different human cancer cells." (PMID 39596123, 2024). "Collectively, these results demonstrate that both SREBF1 and SREBF2 support PDAC cell and tumor growth, suggesting that SCAP may be a better therapeutic target than either SREBP1 or SREBP2 alone." (PMID 39240063, 2024). "Then, we conducted SCENIC analysis to explore the transcriptional regulation driving the acquisition of the cholesterol-related Tumor-Modifying state in neutrophils which revealed activation of BHLH family transcription factors (BHLHE40, ETV5, OLIG2, and SREBF1) within the Neu-T-CCL3 cluster." (PMID 38822440, 2024). "Although the SREBF1 inhibitor fatostatin has been reported to suppress tumor growth and activity, its effect on PCa cells has not yet been characterized." (PMID 38064101, 2024). "In addition, we further investigated the effects of BMS‐303141 on the expressions of lipid synthesis‐related proteins including SREBF1, MOGAT2, FASN, ACC1, ACS and ACLY in ESCC cells and xenografted tumour tissues by Western blot." (PMID 38426936, 2024). "Here, we found SREBF1 and SREBF2 genes also exhibited increased expressions in tumor tissues." (PMID 37164975, 2023). "SREBF1/2 KD reduced de novo lipogenesis from acetate and tumor growth in vivo, whereas the overexpression of mature SREBP1/2 increased lipogenesis and tumor growth." (PMID 37045819, 2023). "While deletion of Srebf1 did not alter tumour load, deletion of Srebf2 resulted in a significant reduction in tumour burden in age matched KPLS2 compared to KPL mice." (PMID 37202505, 2023). "In addition, a significant positive correlation between the levels of SREBF1 and SREBF2 was also evident in the tumor samples (P=0.0011)." (PMID 36300096, 2022). "In addition, we validated (i) the co-regulatory feedback loop between SREBF1/TP63/KLF5, and (ii) canonical target genes of SREBF1 in fatty-acid metabolism (e.g., ACLY, FASN, and SCD) in xenograft tumor samples." (PMID 34272396, 2021). "In this study, we will perform a comprehensive analysis of SREBF1 expression using multiple publicly available gene expression databases and investigate the correlation of SREBF1 expression in HNSC with sample type, cancer stage, lymph node status, and tumor grade." (PMID 37090107, 2023). "We next investigated the regulatory mechanism of TP63 on SREBF1 transcription in SCC, focusing on ESCC model because compared with HNSC and LUSC, ESCC not only showed the highest expression of SREBF1, but also had the highest tumor/normal ratio (that is, the greatest upregulation in tumors)." (PMID 34272396, 2021). "As cancer cells present higher expression of SREBF1 than normal cells, the observed effect of Yarrow SFE on SREBF1 could explain the specificity against tumor cells, being normal cells more protected." (PMID 30913248, 2019).
cancer (307 papers, 2006 to 2026). A tumor composed of atypical neoplastic, often pleomorphic cells that invade other tissues. "The dysregulation of SREBF1 activity has been associated with a number of pathological conditions, including cardiovascular disease, certain types of cancer, and non-alcoholic fatty liver disease." (PMID 40668814, 2025). "In this research, we have found SREBF1 genetic alterations, such as mutations and amplification in different forms of cancers." (PMID 40668814, 2025). "We systematically analyzed the characteristics of the SREBF1 from many aspects of pan-cancer, including expression, survival, prognosis, genetic mutation, and immune cell infiltration." (PMID 40668814, 2025). "We also by utilizing the GEPIA2.0 tool obtained the top 100 genes associated with SREBF1 expression in pan-cancer." (PMID 40668814, 2025). "SREBF1 expression in pan-cancer was analyzed using the Cancer Genome Atlas (TCGA) and Genotype-Tissue Expression (GTEx) data, and the association between SREBF1 expression and clinical characteristics of HNSC patients was examined using the UALCAN database." (PMID 37090107, 2023). "Others have shown that Srebf1c KO causes peripheral neuropathy in mice and that SREBF1 is crucial for cancer cell growth and viability." (PMID 33151932, 2020). "Another example of connection between 2 functional groups is the association, retrieved by text mining, between MYC and SREBF1 (Cancer and Lipid signaling and cholesterol metabolism, respectively)." (PMID 28962550, 2017). "Notably, our analysis revealed a body weight-associated disparity in SREBF1 protein expression across cancer types." (PMID 40668814, 2025). "We explored the gene mutations of SREBF1 in various cancers." (PMID 40668814, 2025). "The association between the SREBF1 expression and checkpoints in pan-cancer was also evaluated." (PMID 40668814, 2025). "Several groups reported the upregulation of SREBF1 in cancer, underlying its pro-tumorigenic roles." (PMID 41174748, 2025). "Sterol regulatory element-binding protein 1 (SREBP1), also known as SREBF1 (sterol regulatory element-binding transcription factor 1), has recently been implicated in cancer progression and in association with clinical status and poor prognosis in different malignancies." (PMID 31861383, 2019). "However, the studies, demonstrating the relationship between SREBF-1 genetic polymorphisms and cancers, are rare." (PMID 24614076, 2014). "Interestingly, yarrow-Sep inhibited key lipid metabolic targets in CRC cells extensively shown to be implicated in cancer dissemination and prognosis —SREBF1, FASN, ABCA1 and HMGCR— and epithelial to mesenchymal targets—CDH1, ATP1B1, CDH2 and Vimentin—augmenting cell adhesion." (PMID 38576446, 2024). "Using genome-wide pleiotropy and colocalization analysis, we identified 60 colocalized susceptibility loci shared by CAD and site-specific cancer, of which 43 are novel, including loci at TERT, MYO9B, and SREBF1." (PMID 40874306, 2025). "The study sheds light on the various roles of SREBF1 in different types of cancer and reveals new perspectives on the potential influence of the SREBF1 in pan-cancer." (PMID 40668814, 2025). "To better understand the effect of SREBF1, we initially evaluated the level of SREBF1 expression in different cancers." (PMID 40668814, 2025). "Among them, the module with the strongest correlation with SREBF1 activity was epithelial cells-M1, with correlation coefficients of 0.91, 0.84, and 0.39 in the Normal, Primary cancer, and CRPC groups, respectively." (PMID 39988626, 2025). "The expression of SREBF1 was significantly increased in most types of cancers, only in GBM and PCPG with lower expression levels." (PMID 40668814, 2025). "The findings indicated that SREBF1 has the potential to be a new prognostic and immune-related biomarker for cancer patients." (PMID 40668814, 2025). "The upregulation of SREBF1 promotes cancer cell survival under stress and contributes to chemoresistance." (PMID 40781643, 2025).
cancer (continued). "Sterol Regulatory Element-Binding Protein 1 (SREBF1), a central regulator of lipid metabolism, has unclear pan-cancer roles and clinical implications." (PMID 40668814, 2025). "This study integrated various databases and functional experiments to systematically investigate the heterogeneous characteristics of SREBF1 across cancers." (PMID 40668814, 2025). "Overall, the findings imply that SREBF1 has the ability to serve as a prognostic marker in multiple types of cancer." (PMID 40668814, 2025). "We observed that SREBF1 activity was highest in epithelial cells from primary cancer samples and accordingly divided cells into SREBF1_POS and SREBF1_NEG groups based on the transcriptional activity of epithelial cells to observe the differences between them." (PMID 39988626, 2025). "The RSS values of SREBF1 were higher in primary cancer and CRPC samples, with values of 0.32 and 0.40, respectively, while the value was only 0.21 in the Normal sample." (PMID 39988626, 2025). "And the finding demonstrated a strong correlation between elevated levels of immune checkpoints and the SREBF1 in ACC, notably KIR2DL3, IL2RA, CD80, IFNG, BTN3A2, and IL1A, also IFNA1 wass significantly associated with SREBF1 in the majority of cancers." (PMID 40668814, 2025). "Both the TF activity and expression of androgen receptor (AR) and sterol regulatory element binding transcription factor 1 (SREBF1) showed significant upregulation in cancer cells from MBC, compared with FBC." (PMID 37696831, 2023). "While cg08129017 was consistently hypermethylated across all analyses, differential expression analysis of the SREBF1 gene annotated to this CpG by ANNOVAR showed a small but significant upregulation in both cancers." (PMID 35710732, 2022). "Cross-cancer analysis identified eight common CpGs, including a strong therapeutic target in SREBF1 (17p11.2)—a key player in lipid metabolism." (PMID 35710732, 2022). "In general, the current data support the notion that LDs and SREBF1 have strong protumor functions in various cancers." (PMID 36139614, 2022). "The accumulation of lipid droplets (LDs) and the high expression of genes involved in LD formation, such as SREBF1 (sterol regulatory element binding transcription factor 1), are attributed to cancer cell resistance against anticancer drugs and poor prognosis." (PMID 36139614, 2022). "Sterol regulatory element-binding transcription factor 1 (SREBP1), which upregulates the transcription of many enzymes of the FA synthesis pathway, is overexpressed in several cancers and has an important role in cell survival." (PMID 34356862, 2021). "Of note, some of these SREBF1-regulated lipids, such as ceramides, have been shown to have prosurvival or antiapoptotic functions in certain cancer cells." (PMID 34272396, 2021). "SREBF1 is a well-known transcription factor that regulates fatty acid metabolism, and it has been reported that the downregulation of PKM2 reduced the expression of SREBF1 in cancer cells." (PMID 33478099, 2021). "SREBF1 has strong protumor functions in several cancer types, including prostate, breast, and liver cancers." (PMID 34272396, 2021). "Taken together, these data shed light on mechanisms of transcriptional dysregulation in cancer, identify specific epigenetic regulators of lipid metabolism, and uncover SREBF1 as a potential therapeutic target and prognostic marker in SCC." (PMID 34272396, 2021). "In cancer cells, SREBF1 protein is also stabilized and activated by the PI3K/Akt/mTOR signaling pathway." (PMID 34272396, 2021). "Combining these observations with the gene expression data, we believe that insulin also has a stimulatory effect on SREBF1 transcription in cancer cells, in agreement with previous findings from liver studies." (PMID 30970006, 2019).
cancer (continued). "We observed that treating infected macrophages with TNFR neutralizing antibodies decreased mTOR phosphorylation at Ser-2448, as previously reported for cancer cells; it also reduced expression of SREBF1, an mTORC1-activated gene." (PMID 30161232, 2018). "Next, we assessed the prognostic value of SREBF1 in pan-cancer OS and DFS." (PMID 40668814, 2025). "All the findings indicated that SREBF1 could be a valuable prognostic biomarker in many types of cancers as a novel therapeutic strategy." (PMID 40668814, 2025). "But the precise role of SREBF1 in other cancer immune function is still being elucidated." (PMID 40668814, 2025). "Although few studies have demonstrated that the overexpression of SREBF1 is closely related to many types of tumors, in HCC, the overexpression of SREBF1 is considered to be one of the major factors causing the proliferation and metastasis of cancer cells." (PMID 40668814, 2025). "In our research, we comprehensively analysed SREBF1 in several cancers in our research." (PMID 40668814, 2025). "Then, the protein levels of SREBF1 in pan-cancer tissues were further analyzed." (PMID 40668814, 2025). "We initially assessed the prognostic value of SREBF1 in pan-cancer OS." (PMID 40668814, 2025). "In support of our speculation, SREBF1 was evidenced to operate as a key metabolic effector of AR to orchestrate de novo lipid synthesis in cancer cells." (PMID 38369486, 2024). "The H2A-K130ac and SREBF1 (nuclear) levels increased as cancer progressed from the stage I to IV." (PMID 37296155, 2023). "Therefore, multidimensional approaches are needed to explore all the smallest parts of the interplay between SREBF1 expression, lipid metabolism, and LD formation in cancer cells." (PMID 36139614, 2022). "Hence, targeting SREBF1 overexpression and LD formation represents one of the promising strategies in cancer therapy." (PMID 36139614, 2022). "Previous studies have shown that SREBF1 is a key regulator of fatty acid metabolism and plays a pivotal role in the transcriptional regulation of different lipogenic genes that mediate lipid synthesis, thus acting as a cancer promoter in human diseases." (PMID 33902514, 2021). "On the contrary, cells from severe dysplastic (HSIL) and cancer (SCC) groups showed the opposite characteristics including the lowest SREBF1 gene methylation as well as the highest level of mitochondrial DNA and lipid cellular concentration (for HSIL/HPVhr+ and SCC groups)." (PMID 33919178, 2021). "Although the role of AMP-activated protein kinase (AMPK)-sterol regulatory element binding transcription factor 1 (SREBP1) pathway in ferroptosis is related to the type of cancer, the activation of this signaling pathway by ferritinophagy limits the expression of BCAT2 in PDAC cells." (PMID 34955844, 2021). "For example, genes assigned to ubiquitous peaks were responsible for the canonical role of SREBF1 in lipid metabolism, whereas transcripts assigned to ESCC-specific peaks were enriched in many cancer-associated signaling pathways, including ErbB and mTOR pathways." (PMID 34272396, 2021). "Indeed, SREBF1 has been shown to be vital to cancer cell proliferation both in vitro and in vivo; likewise, PPARG has been shown to be vital in insulin-stimulated cancer cell proliferation." (PMID 34769312, 2021). "Previous research has primarily focused on SREBF1’s role as transcription factors controlling the expression of downstream genes, with evidence suggesting that it regulates hundreds of cis-regulatory elements across the squamous cancer epigenome, converging to activate cancer-promoting pathways." (PMID 39962068, 2025). "The mechanism for MIAT to exert chemoresistance to cancer cells is that MIAT can recruit a transcription factor, TATA-box binding protein-associated Factor 1 (TAF1), in the promoter region of sterol regulatory element binding transcription factor 1 (SREBF1) and enhance the expression of SREBF1." (PMID 40781643, 2025).